RNU4-11P (RNA, U4 small nuclear 11, pseudogene)
Gene: Small nuclear RNA gene on chromosome 5 (83,803,554 to 83,803,685, forward strand). Ensembl gene ENSG00000202157.
Homologues: Orthologues: chimpanzee U4 (98% identical), macaque U4 (97% identical). Paralogues in human: RNU4-49P (73% identical), RNU4-10P (72% identical), RNU4-17P (70% identical), RNU4-40P (70% identical), RNU4-81P (70% identical), RNU4-32P (69% identical), RNU4-50P (69% identical), RNU4-15P (68% identical), RNU4-51P (68% identical), RNU4-46P (67% identical), RNU4-36P (65% identical), RNU4-24P (64% identical), and 81 more.